CCM2 (CCM2 scaffold protein)
Diseases named in the same sentence as CCM2 in open-access papers:
CCM2 is named in the same sentence as 36 diseases in open-access papers, as found by Europe PMC text mining. Sharing a sentence is not in itself a finding about the gene and the disease. The quoted sentences say what the papers report.
cerebral cavernous malformation (45 papers, 2012 to 2026). A disorder characterized by malformations in the structure of the capillaries in the brain. "Mosaic inactivation of CCM2 in humans causes cerebral cavernous malformations (CCMs) containing adjacent dilated blood-filled multi-cavernous lesions." (PMID 34013885, 2021). "CCM2 gene (Cerebral Cavernous Malformations 2, adjusted p = 0.022, logFC = 0.331) encodes a scaffold protein that functions in the stress-activated p38 Mitogen-activated protein kinase (MAPK) signaling cascade." (PMID 32184383, 2020). "Genetic investigations revealed constitutional mutations in FLCN, associated with Birt–Hogg–Dubé syndrome (BHD) and CCM2, associated with familial cerebral cavernous malformation." (PMID 27722904, 2017). "Of interest, mutations of CCM2 cause cerebral cavernous malformations which can lead to intracerebral hemorrhage." (PMID 25994285, 2015). "Further research found the mutations of CCM2 gene lead to cerebral cavernous malformations." (PMID 26504844, 2015). "Cerebral cavernous malformation 2 (CCM2) is a component of the CCM signalling complex, which has a role in regulating several signalling cascades, including progesterone signalling." (PMID 40447568, 2025). "Cerebral cavernous malformation (CCM) is a vascular disease caused by mutations in the CCM1/KRIT1, CCM2, or CCM3/PDCD10 genes." (PMID 39402138, 2024). "The capillary-venous pathology cerebral cavernous malformation (CCM) is caused by loss of CCM1/Krev interaction trapped protein 1 (KRIT1), CCM2/MGC4607, or CCM3/PDCD10 in some endothelial cells." (PMID 37019926, 2023). "Deletions in the CCM1, CCM2, and CCM3 genes are a common cause of familial cerebral cavernous malformations (CCMs)." (PMID 36555281, 2022). "The PDCD10 gene encodes the highly conserved PDCD10 adaptor protein that forms a protein complex with other cerebral cavernous malformation (CCM) disease–associated proteins, KRIT1 and CCM2, in endothelial cells to maintain vessel integrity." (PMID 34156031, 2021). "CCM1, CCM2, and CCM3 loss-of-function mutations cause the formation of cerebral cavernous malformations." (PMID 32226439, 2020). "Cerebral cavernous malformation (CCM) is an inherited vascular disease that occurs when a second somatic mutation causes a loss of CCM1/KRIT1, CCM2, or CCM3 proteins." (PMID 29364115, 2018). "Here we present a case of BHD syndrome and hereditary cerebral cavernous malformations due to the combination of pathogenic variants in both FLCN and CCM2 in the same individual." (PMID 27722904, 2017). "Mutations in CCM1 (aka KRIT1), CCM2, or CCM3 (aka PDCD10) gene cause cerebral cavernous malformation in humans." (PMID 27513872, 2016). "Mutations in the genes KRIT1, CCM2, and PDCD10 are known to result in the formation of cerebral cavernous malformations (CCMs)." (PMID 27896269, 2016). "Cerebral cavernous malformations are fragile blood vessel conglomerates in the central nervous system that are caused by mutations in the CCM1/KRIT1, CCM2 or CCM3 genes." (PMID 26698571, 2015). "However, expression of ADAMTS5 in brain endothelial cells of Ccm2-deficient mice aggravated cerebral cavernous malformation (CCM) lesion burden and shortened the life span of Ccm2-deficient mice." (PMID 42144952, 2026). "Adult ccm2 CRISPR zebrafish develop typical cerebral cavernous malformation (CCM) lesions." (PMID 34013885, 2021). "It localizes on mouse chromosome 11, in the intervening region of Myo1g (Myosin IG) and Ccm2 (Cerebral cavernous malformation 2) protein-coding genes, with well-defined gene structure and a binding peak of myogenic master transcription factor, MyoD on its promoter region." (PMID 32483152, 2020). "Cerebral cavernous malformations can occur sporadically or as a consequence of inherited loss-of-function mutations in the familial cavernoma genes cerebral cavernous malformation 1, 2 and 3 (CCM1, CCM2, and CCM3)." (PMID 31052208, 2019).
cerebral cavernous malformation (continued). "Cerebral cavernous malformations are characterized by the presence of vascular lesions that are most prevalent in the brain and can occur sporadically or through a familial condition from mutations in CCM1/KRIT1, CCM2/Malcavernin, or CCM3/PDCD10 [reviewed in]." (PMID 30181117, 2018). "We observed that “Generic Binding Proteins” were enriched in the MapsloBTlo region of the graph and corresponded to weakly connected genes; examples at the lowest end (Maps = 1, BT = 0) include CCM2 (cerebral cavernous malformation 2), CD96, and CDH17 (liver-intestine cadherin)." (PMID 22548703, 2012). "Mutations in the cerebral cavernous malformation (CCM) genes, KRIT1, CCM2, and PDCD10, cause CCM disease." (PMID 36692953, 2023). "Loss-of-function mutations are known in one of the three CCM genes: Krev interaction trapped 1 (CCM1/KRIT1), cerebral cavernous malformations 2 (CCM2) and programmed cell death 10 (PDCD10) predisposes to CCMs5,6." (PMID 31796831, 2019). "Previously, we showed that propranolol reduces experimental murine cerebral cavernous malformations (CCMs) and prevents embryonic caudal venous plexus (CVP) lesions in zebrafish that follow mosaic inactivation of ccm2." (PMID 39991834, 2025). "We demonstrate that TLNRD1 is a component of the cerebral cavernous malformations (CCM) complex through its direct interaction with CCM2, which is mediated by a hydrophobic C-terminal helix in CCM2 that attaches to a hydrophobic groove on the four-helix domain of TLNRD1." (PMID 39013281, 2024). "Cerebral cavernous malformations are slow-flow thrombi-containing vessels induced by two-step inactivation of the CCM1, CCM2 or CCM3 gene within endothelial cells." (PMID 34307446, 2021). "The set includes images of the control cells (wild-type HUVEC) and cells with knockdown (KD) of the three Cerebral Cavernous Malformation (CCM) proteins, CCM1 (or KRIT1), CCM2, and CCM3 (or PDCD10), which disrupts the integrity of multicellular mesh." (PMID 32881897, 2020). "Great progress has been made during the last decade in understanding the biological roles of the three known CCM proteins—KRIT1, CCM2, and CCM3—and their role in the pathogenesis of cerebral cavernous malformation (CCM) disease, revealing stunning complexity." (PMID 30658464, 2019). "Src activity has been reported to inhibit the Rho/Rock pathway, a pathway also inhibited by Pak2/Pak4, Rasip1/Arhgap29, and the cerebral cavernous malformation (CCM) proteins, CCM1 and CCM2." (PMID 26812085, 2016). "For instance, the Nogo-B receptor (NgBR), expressed on the surface of BECs, modulates the expression of cerebral cavernous malformation (CCM) genes, CCM1 and CCM2, through a HAT from the MYST family, known as histone acetyltransferase binding to ORC1 (HBO1; MYST2)." (PMID 41566325, 2026).
cavernomas (6 papers, 2014 to 2025). "Familial cavernomas, associated with mutations in CCM1, CCM2, and CCM3 genes, have broadened our understanding of the pathophysiology of these lesions." (PMID 40217805, 2025). "We previously found that arresting blood flow prevents aberrant intussusceptive angiogenesis and the resulted CVP cavernomas in ccm2 CRISPR embryos." (PMID 39991834, 2025). "We previously found that the anti-adrenergic S enantiomer rather than the R enantiomer inhibited development of embryonic CVP cavernomas in ccm2 CRISPR zebrafish." (PMID 39991834, 2025). "Cavernous hemangiomas may occur sporadically or be inherited, with the latter associated with loss-of-function mutations in the KRIT1/CCM1, CCM2, or PDCD10/CCM3 genes." (PMID 40963940, 2025). "Combined with the capacity of mosaic expression of klf2a to cause CVP dilation, these results show that mosaic expression of CCM2 leads to mosaic KLF2a expression and abortive intussusceptive angiogenesis that obstructs the lumen to form these cavernoma-like lesions." (PMID 34013885, 2021). "Inhibition of VEGFR2 does not affect the overexpression of KLF2 or KLF4 after CCM2 loss, but it can partially prevent the development of cavernomas in CCM1-deficient animals." (PMID 33348877, 2020). "In ccm2 CRISPR embryos, KLF2a was both upregulated in a mosaic fashion and required for CVP dilation; we therefore asked whether mosaic upregulation of KLF2a expression per se causes cavernoma formation." (PMID 34013885, 2021). "The patchy increase in KLF2a expression in the CVP endothelial cells of ccm2 CRISPR embryos and requirement for blood flow suggested the possibility that these two factors led to the formation of cavernomas in the CVP." (PMID 34013885, 2021).
neuroblastoma (5 papers, 2014 to 2022). Neuroblastoma (NB) is the most common solid, extracranial childhood tumor. "In contrast, CCM2 is thought to suppress tumors by mediating TrkA-dependent death in medulloblastomas and neuroblastomas." (PMID 36497468, 2022). "TrkA expression indeed induced cell death of neuroblastoma cells and required CCM2 as a primary effector." (PMID 24959744, 2014). "CCM2 is produced in neuroblastomas and glioblastomas, but not in other cancer cells." (PMID 30850602, 2019).
endothelial dysfunction (3 papers, 2022 to 2025). In vascular diseases, endothelial dysfunction is a systemic pathological state of the endothelium (the inner lining of blood vessels) and can be broadly defined as an imbalance between vasodilating and vasoconstricting substances produced by (or acting on) the endothelium. "Our data from CCM2 knockout iPCS-derived endothelial cells reveal a loss of tri-methylation at sites linked to endothelial dysfunction in CCM." (PMID 39402138, 2024). "Borikova and colleagues reported a marked increase in total RhoA protein levels after the loss of expression of CCM1, CCM2, or CCM3 and demonstrated that knockdown of RhoA effectively reverses endothelial dysfunction caused by CCM deficiency." (PMID 35316220, 2022). "However, it is also possible that endothelial dysfunction will develop with different dynamics upon CCM1, CCM2, or CCM3 inactivation." (PMID 40478324, 2025).
medulloblastoma (3 papers, 2016 to 2022). A malignant, invasive embryonal neoplasm arising from the cerebellum. "Subsequent findings show that STK25 can phosphorylate CCM2 and initiate death signaling in medulloblastoma cells." (PMID 29896440, 2018).
vascular malformation (3 papers, 2020 to 2025). A non-neoplastic disorder that is the result of defects of vascular morphogenesis. "In addition, CCM2 and NOTCH3 were reported to be associated with vascular malformations and multiple cerebral cavernous malformations." (PMID 40584829, 2025).
breast carcinoma (2 papers, 2022). "To validate our TCGA expression profiling and our recent findings that CCM2 expression is frequently perturbed in breast tumors, we further investigated additional breast cancer tissue pairs using different panels with larger sample sizes." (PMID 35971177, 2022). "Similarly, our recent works also demonstrated that CCM2 is the cornerstone for the stability and functionality of the CSC in both breast cancer cells and zebrafish Ccm1/2 mutant strains." (PMID 36077089, 2022).
Cognitive impairment (2 papers, 2017 to 2024). Abnormal cognition is characterized by deficits in thinking, reasoning, or remembering. "In conclusion, we presented a family with four affected members from three generations carrying a CCM2 gene mutation, in which detailed neuropsychological evaluation suggested that memory complaints and cognitive impairment could be an important unrecognized finding in FCCM." (PMID 37392320, 2024).
hemorrhage (2 papers, 2020 to 2023). Loss of blood from the vascular compartment to the exterior or into nonvascular body space as a result of rupture or severance of the blood vessels. "The 5-year cumulative risk was higher in subjects with symptomatic hemorrhage at presentation (33.3%), CCM2 genotype (33.3%), presence of at least one CCM in the brainstem at first brain MRI (26.7%), and positive family history (20.7%)." (PMID 36198887, 2023). "For instance, we found a novel mutation in CCM2, p.(Pro55Argfs*9), in a patient with subcutaneous venous lacunae and cerebral cavernous angioma: the latter can increase the risk of hemorrhage and/or seizure." (PMID 33105631, 2020).
intracerebral hemorrhage (2 papers, 2015 to 2025). A cerebrovascular disorder characterized by bleeding into one or both cerebral hemispheres including the basal ganglia and the cerebral cortex. "The condition is caused by mutations in KRIT1 (CCM1), CCM2 (malcavernin), or PDCD10 (CCM3) and may lead to intracerebral hemorrhage (ICH) or non-hemorrhagic focal neurological deficits (FNDs), potentially leading to severe disability and even death." (PMID 41561324, 2025).
atherosclerosis (1 paper, 2019). A disease characterized by the build-up of fatty material and calcium deposition in the arterial wall resulting in partial or complete occlusion of the arterial lumen. "Consistent with a potential role for KRIT1 in genetic susceptibility to atherosclerosis, two recent genome-wide association studies (GWAS) have implicated another CCM gene, CCM2, in coronary artery disease (CAD), a condition that is usually caused by atherosclerosis." (PMID 31590384, 2019).
breast tumors (1 paper, 2022). "Increased CCM2 expression was observed in breast tumor tissues compared to normal tissues, with statistical significance from the entire collection." (PMID 35971177, 2022).
cardiomyopathy (1 paper, 2021). A disease of the heart muscle or myocardium proper. "However, the abnormal down-expressions of heg1, ccm2, and ccm2l in TFD-induced cardiomyopathy could be restored by NXT treatment confirmed by qRT-PCR validation." (PMID 34775978, 2021).
cerebrovascular diseases (1 paper, 2022). "The NGS data analysis was performed in two steps: initially we considered the three known CCM genes, namely KRIT1 (CCM1), CCM2 and PDCD10 (CCM3), and subsequently extended the analysis to NGS panels, including the “Cerebro” panel composed of 23 genes associated with cerebrovascular diseases." (PMID 35883785, 2022).
colorectal cancer (1 paper, 2025). A primary or metastatic malignant neoplasm that affects the colon or rectum. "The importance of stratified analysis is demonstrated by our findings for a causal role of CCM2 in female-specific colorectal cancer." (PMID 40447568, 2025). "Lastly, one gene (CCM2) was specifically associated with female colorectal cancer risk." (PMID 40447568, 2025).
dementia (1 paper, 2020). Loss of intellectual abilities interfering with an individual's social and occupational functions. "This study showed that CMBs and dementia may be attributed to the interaction between the CCM2 variant and the APOE genotype." (PMID 33352859, 2020).
Greig cephalopolysyndactyly syndrome (1 paper, 2023). Greig cephalopolysyndactyly syndrome (GCPS) is a pleiotropic, multiple congenital anomaly syndrome. "Notably, 5/6 cases with variants of CCM2 had no single nucleotide variants but deletions of variable size that can also encompass additional flanking genes, including GLI3, leading to two cases of Greig cephalopolysyndactyly syndrome." (PMID 36198887, 2023).
malignant glioma (1 paper, 2019). A grade III or grade IV glioma arising from the central nervous system. "In addition to that, lncRNA HOXA-AS2 (CCM2 locus) regulates malignant glioma and vasculogenic mimicry formation." (PMID 31796831, 2019).
rectal cancer (1 paper, 2025). A primary or metastatic malignant neoplasm that affects the rectum. "We highlight subsite-specific effects, such as rectal cancer risk linked to LAMC1, a clinically actionable drug target, and identify CCM2 expression as a female-specific CRC risk factor involved in progesterone signalling." (PMID 40447568, 2025). "We also identify a female-specific association with CRC risk for CCM2 expression and subsite-specific associations, including LAMC1 with rectal cancer risk." (PMID 40447568, 2025).
tumor (6 papers, 2019 to 2025). "PDCD10 (CCM3) is a member of the CCM family, which includes CCM1 and CCM2 reported to be involved in tumor metastasis, and in many cardiovascular diseases." (PMID 32483426, 2020). "We concluded that the Dr-TrkA triggers apoptosis in tumor cells expressing CCM2 protein, acting similarly to that of TrkA." (PMID 30850602, 2019). "Finally, a recent study reports that expression of Krit1, Ccm2, and Pdcd10 are reduced in metastatic breast cancer tissues compared with the primary tumor, which indicates that CCM proteins might participate in tumorigenesis and metastasis." (PMID 38980708, 2024). "Some studies have found higher relative RNA expression levels of KRIT1 and CCM2 in cancer cell lines, as compared with normal primary cell lines, which would not be expected of a tumor suppressor." (PMID 38980708, 2024). "Interestingly, we observed significant differential expression in HCC patients for CCM2, PGRMC1, and nPRs, along with AFP, demonstrating the importance of the CmPn network in influencing tumor recurrence." (PMID 36980321, 2023). "Interestingly, our analysis revealed significant alterations in the expression of CCM2, CCM3, PGRMC1, and nPRs across various tumor-staging categories." (PMID 35971177, 2022).
cancer (3 papers, 2019 to 2026). A tumor composed of atypical neoplastic, often pleomorphic cells that invade other tissues. "Among these, CpG sites associated with ZNF667, TEAD1, HDAC4, MSI2, and CCM2 were predominantly hypermethylated, while malignant tumors overall exhibited lower methylation levels compared to the benign group." (PMID 41597272, 2026). "Recently, several studies also investigated the roles of CCM1 and CCM2 in cancers." (PMID 36497468, 2022). "Notably, a recent study systematically analyzed the expression of CCM1, CCM2, and CCM3 in various types of cancers, indicating that differential expression patterns of the CSC may be associated with certain types and grades of cancers." (PMID 36497468, 2022).
CCM2 also shares sentences with these, for which no sentence is quoted: Stroke (3 papers); genetic disease (2); hemorrhagic stroke (2); angiomas (1); capillary malformation (1); cardiovascular diseases (1); cervical cancer (1); glioblastoma (1); Hyperglycemia (1); ischemic stroke (1); Leukoencephalopathy (1); pulmonary arterial hypertension (1); Smith-Magenis syndrome (1); vascular dementia (1); Wilms tumor (1).